SYK (spleen associated tyrosine kinase)
Diseases named in the same sentence as SYK in open-access papers (continued):
Sharing a sentence is not in itself a finding about the gene and the disease.
cancer (continued). "Three major mechanisms through which SYK may affect cancer cell properties have been identified: SYK promoting cell survival through anti-apoptotic factors, SYK altering cellular differentiation programs regulating EMT and SYK altering cell motility." (PMID 28957395, 2017). "A similar trend was observed for the average SYK copy number change in these cancer subtypes." (PMID 24523870, 2014). "Given the central role of SYK in transferring activated immunoreceptors within B-cells, lower SYK gene expression may be involved in dampening the immune response against cancer cells." (PMID 24308539, 2013). "While SYK expression showed associations with sensitivity to several targeted agents, such correlations are inherently dependent on heterogeneous cancer cell lines and may not directly reflect the biology of the GBM microenvironment." (PMID 41463192, 2025). "However, high TGF-β1 expression coupled with low SYK expression could be used to predict de novo resistance to either c-Metis or EGFRis in the CCLE database or in the representative cancer cell lines." (PMID 37183231, 2023). "Previous studies demonstrated that USP10 could deubiquitinate and stabilize Yes-associated protein (YAP)/PDZ-binding motif (TAZ), HDAC6, FMS-like tyrosine kinase 3 (FLT3), spleen tyrosine kinase (SYK) and topoisomerase Iiα (TOP2α), thus promoting cancer progression." (PMID 36163081, 2022). "Finally, we tested whether DDR1-mediated NET-induced cancer cell invasion was through the PKCθ/SYK/NF-κB axis." (PMID 34237033, 2021). "Since spleen tyrosine kinase (SYK), a cytosolic nonreceptor tyrosine kinase interacting with immune receptors, has been previously associated with malignant transformation and cancer cell proliferation, we aimed to assess its role in ETV6-RUNX1 cell survival and prognosis." (PMID 31817853, 2019). "Compound F08060425 affects key pathways like cytokine signaling and the Adaptive immune system, interacting with genes FLT3, SYK, and ROCK1, indicating its role in immune modulation and potential applications in cancer therapy." (PMID 39286631, 2024). "Although the overexpression of SYK(S) did not alter proliferation and metastasis, SYK(S) is important in the chemotherapeutic treatment of CRC, Both SYK(L) and SYK(S) can increase the sensitivity of CRC cells to 5-FU, which is significant in cancer treatment." (PMID 37664052, 2023). "Notably, the PI3K-AKT pathway, a key cancer-related signaling pathway in RB tumorigenesis, is dysregulated and its activator, spleen tyrosine kinase (SYK), is significantly upregulated in retinal organoids, which could be the basis for the development of potential drugs targeting SYK." (PMID 37359513, 2023). "According to our results, SYK, KDR, and FLT1 levels in cancer tissues were 3.7 times, 1.7 times and 1.3 times higher than those in normal tissues, respectively." (PMID 35435107, 2022). "Among the top 50 genes (most significantly and synergistically downregulated by JQ1 and panobinostat combination), we identified SYK and MSI1 genes as the most cancer relevant genes, particularly considering their involvement in neurodevelopment." (PMID 36357906, 2022). "Among these, we identified SYK (spleen tyrosine kinase) and MSI1 (Musashi1) as the most cancer-relevant genes." (PMID 36357906, 2022). "Together, these results provide evidence that DDR1 stimulates CXCL5 production through a PKCθ/SYK/NF-κB signaling cascade and that CXCL5 from cancer cells induces neutrophils to form NETs and thereby enhances metastasis." (PMID 34237033, 2021). "Taken together, we conclude that collagen stimulates pancreatic cancer cells to produce CXCL5 through a DDR1/PKCθ/SYK/NF-κB pathway, and as a result, CXCL5 induces TANs to form NETs and promote cancer cell invasion and metastasis." (PMID 34237033, 2021). "The degradation of the MYC protein, combined with transcriptional downregulation of SYK, GCN5, and MYC, significantly reduces the cancer promoting properties of MYC." (PMID 31645904, 2019).
cancer (continued). "A panel of eight cancer driver genes (CCNE1, TPX2, ELF3, FANCL, JAK2, GSK3B, CEP76, and SYK) were differentially expressed in recurrent TNBCs, and were also overexpressed in TCGA and METABRIC." (PMID 30665374, 2019). "Overall, our data suggest that SYK can be targeted using selective inhibitors like entospletinib in ESCC and these findings can be extrapolated in cancers where SYK overexpression has been reported." (PMID 29719615, 2018). "For example, PLEC, ANXA10, EHF, SLC4A, and CUL4A are expressed at high levels in MDA-MB-231 relative to MCF-7 cells, and MAGED1, SYK, and EPCAM are expressed at higher levels in triple-negative cancer tissues relative to non-invasive control tissues." (PMID 26053433, 2015). "In agreement with our results, in the Cancer Cell Line Encyclopedia, 35 out of 49 SCLC cell lines tested overexpress SYK (> 2 fold of the median centered intensity values)." (PMID 24564859, 2013). "Furthermore, these transcription factors are enriched in cancer-related kinases such as lymphocyte-specific protein tyrosine kinase (LCK), LYN proto-oncogene (LYN), spleen tyrosine kinase (SYK), Janus kinase 3 (JAK3), and FER tyrosine kinase (FER)." (PMID 40612864, 2025). "When HSPA5 over-expression negatively affects cancer treatment outcomes, targeting the link between the UPR and SYK kinase pathways with rationally designed SYK inhibitors may be effective." (PMID 37221596, 2023). "Besides, other SYK inhibitors, such as Entospletinib (GS-9973) and Cerdulatinib (PRT062070), are also identified as effective anti-cancer drugs in both pre-clinical and clinical trials." (PMID 36568669, 2022). "Mutations on DEPTOR Tyr 289 have not been reported in cancer, whereas mutations within EPHB2 and SYK in various malignancies were described in multiple publications." (PMID 34634301, 2021). "In hematopoietic malignancies, the non-receptor spleen tyrosine kinase (SYK) mainly contributes to cancer cell survival and proliferation by mediating tonic and chronic signaling through B-cell antigen receptors in different B-cell-derived lymphoma types." (PMID 33670716, 2021). "Another hub gene, such as KITLG, PTGS2, SYK, FLT1 (VEGFR-1), GNA13, etc. could also regulate invasion and metastasis of cancer 42-48." (PMID 32194783, 2020). "Also, FCGR1A is involved in many pathophysiological processes and is closely related to FCGR3A, SYK, and HCK in various cancers." (PMID 33344503, 2020). "Co-culture of sialyl-Tn+ cancer cell line and M-CSF–induced human macrophages or Siglec-15+ myeloid cell line enhanced the myeloid cell production of TGF-β (a pleiotropic cytokine that promotes epithelial-mesenchymal transition and metastasis of cancer cells), which was dependent on DAP12 and SYK." (PMID 31900164, 2020). "In contrast, immune-related kinases (ZAP70, SYK, ITK, and CSF1R) displayed reduced activity, implicating dampened immune signaling in pathways like PD-L1 Expression and PD-1 Checkpoint in Cancer (hsa05235), T Cell Receptor Signaling (hsa04660), and B Cell Receptor Signaling (WP23)." (PMID 41387887, 2025). "As a nonreceptor cytoplasmic tyrosine kinase, SYK (spleen tyrosine kinase) is a key mediator in a variety of inflammatory cell and immune signaling pathways and has been proven to be a useful drug target for many cancers." (PMID 33842538, 2021). "This EPH receptor/SYK/DEPTOR mechanism, which bypasses the canonical pathway of mTOR activation, could potentially explain why so many cancers show constitutive mTOR activation without mutations in the PI3K/AKT pathway." (PMID 34634301, 2021). "The role of SYK in human cancers is not completely established." (PMID 33540941, 2021). "Inhibition of SYK activity by SYK-specific inhibitors such as PRT060318 and fostamatinib disodium provides great clinical outcome to certain cancer patients with abnormal SYK activities, indicating that subtype I patients may be benefited from SYK-specific kinase inhibitors." (PMID 28178664, 2017).
infection (18 papers, 2016 to 2026). The state of being infected such as from the introduction of a foreign agent such as serum, vaccine, antigenic substance or organism. "The kinase-substrate phosphomotif pattern analysis revealed several kinases, including EEF2K, HASPIN, MAPK9, MAST2, and Spleen tyrosine kinase (SYK), that can phosphorylate multiple NiV proteins at various sites, suggesting regulatory roles during infection." (PMID 41424949, 2025). "To test the importance of these mutations on FCRL3 clustering and SYK recruitment, we first monitored colocalization of FCRL3, SYK, and Y. pestis in HeLa cells overexpressing FCRL3 at 15-, 30-, and 60-min post infection." (PMID 39677730, 2024). "To confirm lentivirus-mediated expression, we examined GFP-DCs and SYK-DCs by qRT-PCR analysis at 7 days after infection." (PMID 29372378, 2018). "In contrast, during infection of dendritic cells by C. albicans, the priming signal only requires the CLR/Dectin-1/SYK pathway." (PMID 41249509, 2025). "During infection of macrophages by C. albicans, pro-IL-1β transcription is regulated through both TLR2/MyD88 and CLR/Dectin-1/SYK pathways, activating the downstream CARD9/BCL10/MALT1 complex that is essential for IL-1β secretion." (PMID 41249509, 2025). "CLEC9A-mediated SYK activation specifically promotes the production of CXCL8 and IL-1β, which are central to neutrophil recruitment and activation during the early stage of infection." (PMID 29065139, 2017).
hematological malignancies (16 papers, 2013 to 2025). "Several SYK inhibitors such as fostamatinib and entospletinib are under clinical development primarily for hematologic disorders and B lymphocyte malignancies, with fostamatinib being first approved for the treatment of immune thrombocytopenia." (PMID 40857403, 2025). "Entospletinib, a selective and potent second-generation SYK inhibitor, has completed several clinical trials for patients with hematological malignancies." (PMID 40857403, 2025). "Entospletinib is a second-generation, selective, and potent SYK inhibitor that is currently in clinical development for hematologic malignancies with a favorable short-term safety profile." (PMID 40857403, 2025). "CG-806 (luxeptinib) is a dual BTK/SYK inhibitor in clinical development in hematologic malignancies." (PMID 35296646, 2022). "An important question regarding the pharmacological approaches in hematological malignancies is: what are the potential differences between the SYK inhibitors in leukemic cells and in normal hematopoietic cells?" (PMID 36499034, 2022). "Importantly, however, SYK has been implicated in the transformation of a variety of non-hematologic malignancies as well, and therefore novel approaches to target SYK through such tactics as protein destabilisation could potentially have wide-reaching clinical relevance and application." (PMID 32015510, 2020). "Entospletinib is a selective inhibitor of SYK, which is currently being evaluated in phase II clinical trials for hematological malignancies." (PMID 29719615, 2018). "We further evaluated efficacy of SYK selective inhibitor entospletinib that is already in phase II clinical trials for the treatment of hematological malignancies." (PMID 29719615, 2018). "SYK gene fusions or translocations have been reported in hematologic malignancies, in which a driver function for overexpressed SYK has also been postulated." (PMID 24564859, 2013). "SYK has been previously investigated most extensively in the context of lymphocyte development and as a therapeutic target in hematologic malignancies." (PMID 24564859, 2013). "Together, these observations have formed a rationale for SYK-targeted therapy in hematological malignancies with small molecule kinase inhibitors." (PMID 24564859, 2013). "However, our data supported an effect of SYK inhibition particularly in FLT3 mutated cases, and special TAK-659, which has inhibitory effects against both FLT3 and SYK, seems promising for use in hematological malignancies." (PMID 36499034, 2022). "It is well established that SYK plays a key role in the survival of a number of different types of hematologic malignancies, with much attention focused on SYK promotion of growth of malignancies of B cell origin and survival attenuated by inhibition or removal of SYK." (PMID 32015510, 2020). "Hyperactivated SYK is a driver oncogene in a number of hematologic malignancies." (PMID 32015510, 2020). "Finally, IPO7 is linked to B cell receptor (BCR) activation through nuclear shuttling of SYK, which might provide another way to target BCR activation and SYK in hematological malignancies." (PMID 32624581, 2020). "SYK, a non-receptor tyrosine kinase, has garnered significant attention in numerous studies as a promising target for hematologic malignancies and inflammation-related diseases." (PMID 38799454, 2024). "However, it should be noted that the Hippo kinase STK4, also identified as a SYK target in DG75 cells, and YAP1, are involved in hematologic malignancies." (PMID 33670716, 2021). "SYK is an oncogenic non-receptor tyrosine kinase involved in hematologic malignancies." (PMID 24564859, 2013).
kidney disease (3 papers, 2020 to 2025). "SYK is activated downstream of DAMP-sensing C-type lectin receptors such as CLEC4E (Mincle, Clec4e) and CLEC7A (Dectin-1, Clec7a) that have been implicated in kidney disease." (PMID 40857403, 2025). "In a preclinical model, SYK upregulation was identified at sites of renal and pulmonary inflammation, and treatment with an SYK inhibitor was completely effective in treating established lung and kidney disease, without hematological toxicity." (PMID 32305129, 2020).
neurodegenerative disease (3 papers, 2023 to 2024). A disorder of the central nervous system characterized by gradual and progressive loss of neural tissue and neurologic function. "Some researchers found that inhibition or knockdown of SYK reduced activation of the mammalian rapamycin signaling pathway and increased tau degradation without affecting tau production, which is of great significance in case of neurodegenerative diseases." (PMID 37506139, 2023). "SYK is important in inflammatory and adaptive immune responses and thus may be involved in neuroinflammation observed in neuro‐degenerative diseases." (PMID 37506139, 2023). "By continuing to expound on SYK signalling and its downstream regulators, more specific disease targets may be revealed, ultimately allowing for refined microglial interventions capable of curbing neurodegenerative disease progression." (PMID 36629045, 2023). "Taken together, our findings suggest that SYK is a key regulator of microglial DAM/MGnD transition and phagocytosis in response to both Aβ‐ and myelin‐driven neurodegenerative diseases." (PMID 36629045, 2023).
bacterial infection (2 papers, 2016 to 2022). "Our data suggest that, in addition to the well-described regulatory role for CARD9 downstream of SYK, it is also possible that CARD9 can act upstream of SYK during bacterial infection." (PMID 27670879, 2016).
blood cancer (2 papers, 2017 to 2018).
hematologic cancers (2 papers, 2023 to 2024). "The spleen tyrosine kinase (SYK) has been validated as a target for the treatment of a number of hematological cancers, autoimmune disorders and other inflammatory conditions." (PMID 37904048, 2024).
inflammation (2 papers, 2021 to 2023). Aberrant reaction of the microcirculation characterized by movement of fluid and leukocytes from the blood into extravascular tissues. "That inflammation, immune system activation and imbalance, and cell proliferation and adhesion migration were mainly affected by HLA-DRA, SYK, CTLA4, VAV1, NRAS, and JAK3 signaling pathways was suggested to be the potential molecular mechanism for pulmonary inflammation and fibrosis in ACO." (PMID 33869177, 2021).
liver (1 paper, 2023). "For example, polylactic-co-glycolic acid (PLGA) NPs with a Spleen Tyrosine kinase (SYK) pathway inhibitor have been used to target and treat macrophages in chronic liver injury induced by steatohepatitis, since SYK is a critical mediator in inflammatory pathways." (PMID 37483594, 2023).
metabolic disease (1 paper, 2017). A congenital disorder (due to inherited enzyme abnormality) or acquired (due to failure of a metabolically important organ) disorder resulting from an abnormal metabolic process. "A better understanding of the regulation of SYK activity and its targets in brown fat and possibly also in white fat thus has the potential to reveal novel avenues towards the treatment of metabolic diseases." (PMID 29235464, 2017).
peripheral neuropathy (1 paper, 2024). A disorder affecting the peripheral nervous system. "Together, the regulation of FCER1G, SYK, and PTK2B on the development of nerve system disease suggests that they most likely contribute to T2DM‐induced peripheral neuropathy." (PMID 38018513, 2024).
SYK also shares sentences with these, for which no sentence is quoted: neuroendocrine tumor (3 papers); angioimmunoblastic T-cell lymphoma (2); autoimmune thrombocytopenia (2); childhood asthma (2); lymphedema (2); marginal zone lymphoma (2); multiple sclerosis (2); osteosarcoma (2); abscesses (1); alcohol (1); alcohol abuse (1); alcoholic steatohepatitis (1); alopecia areata (1); anaplastic large cell lymphoma (1); aortic valve diseases (1); autoimmune hemolytic anemia (1); benign neurofibroma (1); bipolar disorder (1); Bovine mastitis (1); brain injury (1); brain tumors (1); Bruton’s agammaglobulinemia (1); cardiovascular diseases (1); cholangiocarcinoma (1); chronic eosinophilic leukemia (1); colorectal adenocarcinoma (1); coronary heart disease (1); cryptococcosis (1); cutaneous skin melanoma (1); dementia (1).
A further 67 diseases each share a sentence with SYK in 1 paper.